CTLA4 (cytotoxic T-lymphocyte associated protein 4)
Diseases named in the same sentence as CTLA4 in open-access papers (continued):
Sharing a sentence is not in itself a finding about the gene and the disease.
myocarditis (continued). "For C57/BL6J wild type mice, combinational anti-PD-1 (25 mg/kg) and anti-CTLA4 (25 mg/kg) given every 3 days for 5 doses led to myocarditis." (PMID 36672615, 2023). "Abatacept is an agonist of CTLA-4 that alleviates nivolumab-induced myocarditis in lung cancer treatment as well as pembrolizumab-induced myocarditis in melanoma treatment." (PMID 37305530, 2023). "Axelrod et al28 demonstrated the presence of clonal effector CD8+ T populations in the hearts of Pdc1−/−/Ctla4+/− mice that develop spontaneous myocarditis." (PMID 38205352, 2023). "Genetic studies in mice highlight the importance of T cells and immune checkpoints, such as CTLA-4 and PD-1, in myocarditis pathogenesis." (PMID 38137806, 2023). "Genetic knock-out of Ctla4 in mice leads to lymphoproliferative disorders, multiorgan immune infiltration, tissue inflammation, including myocarditis, and premature mortality." (PMID 36979163, 2023). "In this context, reports indicated that knockout mice for CTLA-4 develop lymphoproliferative diseases such as multiorgan lymphocytic infiltration, tissue destruction, myocarditis, and pancreatitis." (PMID 37631034, 2023). "Using the GSE213486 data series, we studied the heart tissues of four-week-old healthy C57BL6 mice and Pdcd1–/–Ctla4+/– mice with myocarditis (simulating dual PD1/CTLA-targeted anticancer therapy in clinical practice)." (PMID 37388276, 2023). "Previous studies have suggested that the combination of anti-CTLA-4 and anti-PD-1 is one of the strongest risk factors for ICI-associated myocarditis." (PMID 37876928, 2023). "We searched the PubMed, Embase, Cochrane Library, and China National Knowledge Infrastructure (CNKI) electronic databases for the following terms: 1) “immune checkpoint inhibitors” or “PD-1” or “PD-L1” or “CTLA-4” and 2) “myocarditis” or “cardiotoxicity”." (PMID 37305530, 2023). "The complementarity of different mechanisms leads to a higher frequency of myocarditis, which is consistent with the higher clinical incidence of myocarditis induced by anti-PD-1/PD-L1 therapy coupled with anti-CTLA-4 therapy." (PMID 37297017, 2023). "Rates of ICI myocarditis have increasingly been reported and development of ICI‐myocarditis alone is associated with high rate of (upwards of 50%) mortality, with more severe ICI‐myocarditis associated with the combined use of anti‐PD1 and CTLA‐4 therapies." (PMID 36128926, 2022). "Immune checkpoint inhibitors (ICIs) which show effect of anti-PD-1 (nivolumab and pembrolizumab), anti-PD-L1 (atezolizumab, avelumab, and durvalumab), and anti-CTLA-4 antibodies (ipilimumab and tremelimumab) also result in side effect of myocarditis." (PMID 36517746, 2022). "Inhibition of the PD-1/PD-L1 pathway resulted in ICI-related myocarditis more often than inhibition of the CTLA-4 pathway (0.41 vs. 0.07%, respectively)." (PMID 36263134, 2022). "Another 57-year-old renal cell carcinoma male also had concurrent myositis and myocarditis after PD-1 and CTLA-4 treatment." (PMID 35844550, 2022). "Alemtuzumab (anti-CD52 mAb) and abatacept, a protein consisting of the human CTLA-4 extracellular domain fused to the Fc portion of IgG, acting as a CTLA-4 agonist, have been employed for the treatment of single cases of glucocorticoid-refractory myocarditis." (PMID 35432346, 2022). "Mice with CTLA4 haploinsufficiency alone developed myocarditis, however of the mice with complete Pdcd1 knockout, approximately 50% of died within 3 months of age." (PMID 36263134, 2022). "In a case report, abatacept, a cytotoxic T-lymphocyte-associated antigen 4 [CTLA-4] agonist, showed the capability to resolve a severe case of glucocorticoid-refractory myocarditis that was induced by the immune checkpoint inhibitor nivolumab." (PMID 35565184, 2022). "It has been reported that dual therapy (anti-CTLA-4 and anti-PD-1/PD-L1) increased the rate of myocarditis than monotherapy (1.22% vs. 0.54%; 5.8% vs." (PMID 35433707, 2022).
myocarditis (continued). "But with the combination of CTLA4 inhibitors, the myocarditis has tripled to 1.33% (32/2,412 patients) (94.6% cases in this study received PD-1/PD-L1 antibodies)." (PMID 35517794, 2022). "A report of two lethal cases of myocarditis in melanoma patients receiving combination anti-CTLA-4/anti-PD-1 therapy showed T-cell infiltrates in the myocardium and skeletal muscle." (PMID 36263134, 2022). "The myocarditis lesions appeared as well in adult CTLA-4 humanized MC38-tumor-bearing mice treated with ipilimumab alone or in combination with anti-PD1." (PMID 36139654, 2022). "There are discrepancies in literature about this as one study in 2018 found anti-CTLA-4 to induce more myocarditis whereas a meta-analysis in 2021 again found more myocarditis cases due to anti-PD-1 (69.4%) than CTLA-4 (20%)." (PMID 36263134, 2022). "A randomized, double-blind, placebo-controlled trial evaluating the safety of ipilimumab (CA184-029), a CTLA-4 inhibitor, in adjuvant treatment of melanoma found a severe to fatal myocarditis incidence of 0.2%5." (PMID 34462476, 2021). "For example, one study showed that nivolumab (PD-1 inhibitor) and ipilimumab (CTLA-4 inhibitor) had almost a 5 times greater incidence of myocarditis compared to single agent nivolumab." (PMID 34434981, 2021). "Abatacept is an agonist toward CTLA-4, preventing costimulation of T cells, and was used in a case of steroid refractory nivolumab induced myocarditis, resulting in a lifesaving treatment." (PMID 34434981, 2021). "In these 101 reports of patients with severe myocarditis after treatment with ICIs, most patients (57%) received anti-PD-1 monotherapy, while 27% of patients received anti-PD-1/PD-L1 plus anti-CTLA-4 combination therapy." (PMID 33413213, 2021). "Clinical case reports have shown fatal cases of fulminant myocarditis following a single dose of anti-PD1 or anti-CTLA4 treatment." (PMID 34049595, 2021). "Strikingly, of those patients who experience myocarditis following combined PD-1 and CTLA-4 blockade, the mortality is greater than 60%." (PMID 35047501, 2021). "Nonetheless, the risk of developing myocarditis is shown to be lower with anti-PD1 drugs, when compared to anti-PDL1 and anti-CTLA4 drugs." (PMID 34441012, 2021). "The decreased expression of Tim-3 and CD80 on mast cells and macrophages reduces the level of cytotoxic T lymphocyte-associated protein 4 (CTLA-4) on the surface of CD4+ T cells, resulting in a decrease in the number of Treg cells and aggravated myocarditis." (PMID 34603337, 2021). "Mortality reported from these cases of myocarditis ranged from 36% for patients treated with anti-PD-1 or anti-PD-L1 antibodies to 67% for patients treated with combination anti-CTLA-4 and anti-PD1/PD-L1 therapy." (PMID 32983574, 2020). "The infiltrating CD68+ macrophages in ICI-induced myocarditis were noted in a patient with fatal myocarditis after a combination of CTLA-4 and PD-1 blockade." (PMID 31022941, 2019). "The importance of CTLA-4 is demonstrated in CTLA-4-knockout mice, who develop early and catastrophic immune hyperactivation causing myocarditis and pancreatitis, and die by 3–4 weeks of age." (PMID 31877721, 2019). "Recently, CTLA-4 was found to be expressed in mononuclear cells infiltrating heart tissue sections from chronically infected subjects with severe myocarditis." (PMID 25152568, 2014). "CTLA-4 expression is also increased in inflammatory heart lesions from chronically infected subjects with intense myocarditis." (PMID 22574131, 2012). "CTLA-4 was also expressed by CD3+ T lymphocytes infiltrating heart tissues from chronically infected subjects with severe myocarditis." (PMID 22574131, 2012). "Tim-3 is a key regulator of inflammation in the heart, providing inhibitory signals during the innate and adaptive immune response to infection that increase expression of CTLA-4 leading to increased numbers of Treg cells and reduction of acute myocarditis." (PMID 23675015, 2007).
myocarditis (continued). "This case report describes a 75-year-old female patient with deficient mismatch repair sigmoid colon adenocarcinoma who developed severe multi-organ irAEs, including myositis, hepatitis, and steroid-refractory myocarditis 25 days after receiving QL1706 (a PD-1/CTLA-4 bispecific antibody)." (PMID 42023214, 2026). "A report indicates that 6 of 7 patients with MG treated with PD‐1/CTLA‐4 inhibitors developed these complications, a pattern sometimes referred to as the ‘triple‐M complication’ (myasthenia, myositis, and myocarditis), which is known for its high mortality and rapid progression." (PMID 40842502, 2025). "Furthermore, cardiac myosin-specific T cells showed higher levels of CTLA-4 expression than bystander T cells in our animal model of ICI-induced myocarditis." (PMID 40606990, 2025). "All of these results point to the possibility that blocking CTLA-4 pathways might precipitate myocarditis and exacerbate its severity." (PMID 40606990, 2025). "CTLA-4 deficit even in Treg cells is capable of myocarditis induction." (PMID 40255399, 2025). "CD8+ T cells were pinpointed as the catalyst for myocarditis in Pdcd1−/− Ctla4+/− mice." (PMID 39039301, 2025). "Another multicenter randomized trial (NCT05335928) is testing whether the early introduction of abatacept, a CTLA-4 agonist and T-cell inhibitor, improves major adverse cardiac event outcomes in patients with ICI-associated myocarditis." (PMID 38791970, 2024). "Fulminant myocarditis spontaneously develops in Pdcd1–/– Ctla4+/– mice." (PMID 39465131, 2024). "However, they reported that both myocarditis and pericarditis were more commonly associated with anti-PD1 and anti-PDL1 than anti-CTLA4 therapy." (PMID 39459012, 2024). "Finally, methylprednisolone has been shown to suppress myocarditis induced by the CTLA-4 inhibitor ipilimumab." (PMID 37305530, 2023). "This study also provided further evidence that the combination of the two agents raised the incidence of myocarditis and stated that, compared to anti-CTLA-4 antibody, anti-PD-1/PD-L1 antibody may be more likely to cause ICI-associated myocarditis." (PMID 37297017, 2023). "Indeed, in a transgenic Ctla4+/−Pdcd1−/− mouse model which resembles ICI-mediated myocarditis in patients, T cell receptor (TCR) sequencing revealed an accumulation of T cells with α-myosin-reactive TCRs in the hearts of these mice [49, 50•]." (PMID 37079251, 2023). "Also, concomitant administration of CTLA-4 and PD-1/PDL-1 inhibition and diabetes mellitus were distinct predisposing factors for the development of ICI-associated myocarditis." (PMID 38045806, 2023). "Our research showed that patients receiving anti-CTLA-4 and anti-PD-1 antibodies may exhibit a higher grade of myocarditis, with 46% incidence of grade 4 myocarditis." (PMID 37876928, 2023). "Anti-PD-1 antibody therapy leads to more cases of cardiac adverse effects than anti-CTLA-4 therapy and several reports and meta-analyses studies have reported increased cases and worse prognosis of myocarditis patients treated with ICIs in combination compared to monotherapies." (PMID 36139654, 2022). "The non-susceptibility of anti-CTLA-4 to pericarditis and myocarditis was due to the difference of disease-specific effects and mechanism, respectively." (PMID 36408225, 2022). "Animal models deficient in cytotoxic t lymphocyte-associated protein-4 (CTLA-4) and programmed cell death protein-1 (PD-1), show T lymphocyte infiltration and severe myocarditis with a rise in cardiac biomarkers, such as troponin and cardiomyocyte necrosis, on pathology." (PMID 35214762, 2022). "The overreporting of myocarditis in patients treated with anti-PD-1 vs. anti-CTLA-4 was noted." (PMID 36354777, 2022). "Indeed, a number of patients treated with anti-PD-1 or PD-L1 show cardiotoxicity, mostly myocarditis, especially in combination with anti-CTLA4 treatment." (PMID 34790707, 2021).
myocarditis (continued). "For example, CTLA-4 knockout mice reportedly develop autoimmune myocarditis caused by CD8+T cells, whereas knockout of PD-1 is associated with anti-cTn autoantibody-mediated myocarditis." (PMID 34291066, 2021). "We discuss the possibility that heightened pro-inflammatory T cell activity (rather than tumor-directed cytolytic activity) was induced by anti-PD-1 and anti-CTLA-4, which could have provoked both rapid tumor resistance mechanisms and myocarditis." (PMID 33603731, 2021). "Detailed analysis of 88 cases from the literature search and our registry showed that myositis induced by PD-1 inhibitors was more frequent than that induced by anti-CTLA-4 agents, revealing a clinically diverse trend including myasthenia gravis and myocarditis." (PMID 34938300, 2021). "In the inflamed myocardia of patients with fatal myocarditis after a combination of CTLA-4 and PD-1 blockade, PD-L1 was expressed on the membranous surface of injured cardiac myocytes and on infiltrating CD8+ T cells and histiocytes of the inflamed myocardium, but not skeletal muscles." (PMID 31022941, 2019). "Other events, such as cardiomyopathy, myocardial fibrosis, myocarditis, and acute heart failure, were also reported in single anti-CTLA-4 or anti-PD-1 treatment, and lethal myocarditis accompanying with myositis was seen in combinatorial treatment, although such cases are rare." (PMID 29473044, 2018). "CTLA-4 expression was mainly detected in CD3+ T cells in areas of severe diffuse myocarditis." (PMID 22574131, 2012). "All 4 heart explants from chronically infected subjects with diffuse severe myocarditis showed a variable number of CTLA-4+ cells (average percentage of CTLA-4+ cells/total infiltrating cells counted = 7,6±6; range = 1–23% in 10 representative fields per patient)." (PMID 22574131, 2012). "Mice lacking Ctla4 in Tregs exhibited dense infiltration of mononuclear cells into the myocardium, resulting in the destruction of myocytes and possibly leading to fulminant myocarditis as cause of death." (PMID 39039301, 2025). "The receipt of combination ICI therapy (e.g., a CTLA-4 inhibitor combined with a PD-1 inhibitor) is the most well-established risk factor for the development of ICI myocarditis, with the combination of nivolumab and ipilimumab carrying a 4.74-fold risk of myocarditis compared to nivolumab alone." (PMID 38472975, 2024). "Therefore, we investigated whether anti‐CTLA‐4 m2a antibody could exacerbate myocarditis using the EAM model." (PMID 38978328, 2024). "Interestingly, Treg-specific deletion of Ctla4 was sufficient to induce myocarditis development." (PMID 36979163, 2023). "Models with combined genetic knockout of Ctla4 and Pdcd1 showed that macrophages and CD8+ T-cells drive the myocarditis." (PMID 41598751, 2026). "Second, it has been reported that combined therapy of CTLA-4 and PD1/PDL1 inhibitors are more likely to induce myocarditis compared with monotherapy of PD1/PDL1 inhibitors." (PMID 40165308, 2025). "There are numerous reports in the literature that describe severe myocarditis following ICI use, with the highest frequency amongst PD-1 and PDL-1/CTLA-4 therapies." (PMID 38406102, 2024). "In CTLA-4-deficient mice, without immunosuppression of CTLA-4, peripheral T cells were overactivated and proliferated, which mediates severe tissue damage, and the mice develop lymphoproliferative diseases with severe myocarditis as well as death within four weeks eventually." (PMID 37297017, 2023). "These distinct immune profiles from CTLA-4 and PD-1 inhibition offer opportunities to characterize the mechanism behind ICI-mediated myocarditis." (PMID 34434981, 2021). "More recently, it was reported that the use of abatacept, a CTLA-4 agonist, induced the resolution of corticosteroid-refractory ICI myocarditis." (PMID 33997442, 2021).
myocarditis (continued). "Moreover, it is unknown if there are differences in ICI myocarditis case characteristics and outcomes based on ICI therapeutic target [programmed cell death protein 1 (PD-1), PD ligand 1 (PD-L1), or cytotoxic T-lymphocyte associated protein 4 (CTLA-4)] or with use of combination therapy." (PMID 40083879, 2025). "Studies conducted on mice lacking PD-1 and CTLA-4 have demonstrated the development of dilated cardiomyopathy and myocarditis." (PMID 38482205, 2024). "Immunoglobulins that bind to CTLA-4 and PD1/PD-L1 have been shown to ameliorate myocarditis." (PMID 37305530, 2023). "In fact, one of the studies demonstrated that knocking out CTLA4 in adulthood with the Cre-Lox recombination system does not lead to myocarditis." (PMID 36672615, 2023). "Alternatively, ICI-induced myocarditis could also be induced in MRL/MpJ-Fas/lpr mice by giving anti-PD-1 (200 μg) and anti-CTLA4 (200 μg) two times per week for 8 weeks." (PMID 36672615, 2023). "Recent evidence suggests that abatacept, a CTLA-4 agonist, may be used as additional immunosuppression for severe ICI–related myocarditis." (PMID 35877565, 2022). "Ctla4+/− Pdcd1−/− mice showed increased troponin levels with cardiac infiltration of CD3, CD8, and CD4 cells, and reduced numbers of Treg cells, similar to that seen in human ICI myocarditis." (PMID 35455289, 2022). "Furthermore, older treatments with CTLA-4 blockade had higher rates of IRAEs and the combination of PD-1 and CTLA-4 inhibition led to increased myocarditis cases." (PMID 33614750, 2021). "Myocarditis rates based on a single center (Massachusetts General Hospital) are 1.14% for all immune checkpoint inhibitors, 0.5% of patients on anti-PD1 alone, and 2.4% with combined anti-PD1/anti-CTLA4 antibodies." (PMID 31002639, 2019). "Additionally, left ventricular dysfunction, even in the absence of myocarditis, has been observed in patients treated with CTLA-4 inhibitors like ipilimumab." (PMID 40255399, 2025). "Instead, animals devoid of PD-1/L1 but with homoallelic CTLA-4 did not develop myocarditis." (PMID 40255399, 2025). "Interestingly, blocking PD-1 or CTLA4 in MRL mice results in increased lymphocyte infiltration without the development of overt myocarditis." (PMID 35455289, 2022). "Likewise, CTLA-4 ablation may lead to the proliferation and infiltration of CD8+ T cells in the heart, resulting in severe myocarditis." (PMID 36142538, 2022). "We only had one patient diagnosed with ICI-related myocarditis, so we could not evaluate the effect of corticosteroids or CTLA-4 agonist abatacept on the outcome of myocarditis patients." (PMID 33736707, 2021). "It is worth mentioning that a significant number of CTLA-4+ T lymphocytes in heart tissues was observed in areas with amastigote nets and intense myocarditis but not in areas with mild myocarditis, providing a link between parasite persistence, disease severity and CTLA-4 expression." (PMID 22574131, 2012). "No CTLA-4+ cells were detected in the 4 remaining cases with mild myocarditis." (PMID 22574131, 2012). "In a large retrospective analysis, myocarditis and pericarditis have been observed more in anti-PD- or anti-PDL-1 monoclonal antibodies relative to those treated with anti-CTLA-4 monotherapy, and this may be due to the increased use of anti-PD-1 or anti-PDL-1 regimens over anti-CTLA-4 monotherapy." (PMID 33842004, 2021). "Thirdly, myocarditis is more prevalent in patients with combined use of CTLA-4 and PD-1/PD-L1, but CTLA-4 has not yet been marketed in the Mainland and was therefore not included in this study." (PMID 34658887, 2021). "ICI-related myocarditis is an irAE that stems from the non-specific, systemic activation of immune cells, a side effect of the ICI action of blocking immunosuppressive signals like PD-1 and CTLA-4 to reactivate T-cell cytotoxicity against tumors." (PMID 41598751, 2026).